ZPR1 (ZPR1 zinc finger)
Diseases named in the same sentence as ZPR1 in open-access papers:
ZPR1 is named in the same sentence as 44 diseases in open-access papers, as found by Europe PMC text mining. Sharing a sentence is not in itself a finding about the gene and the disease. The quoted sentences say what the papers report.
metabolic syndrome (16 papers, 2011 to 2025). A cluster of metabolic risk factors for CARDIOVASCULAR DISEASES and TYPE 2 DIABETES MELLITUS. "Recently, ZPR1 variant rs964184 has been repeatedly linked to high plasma triglyceride levels, metabolic syndrome, type 2 diabetes mellitus (T2DM), and nonalcoholic fatty liver disease (NAFLD), suggesting its involvement in lipid metabolism." (PMID 34746842, 2021). "Like APOE, ZPR1 also participates in lipid metabolism; it lies on chromosome band 11q23.3, and ZPR1 variant rs964184 has been consistently linked to high plasma triglyceride level, metabolic syndrome, T2DM, and NAFLD." (PMID 34746842, 2021). "APOA5 (p = 3.45 × 10−8, FDR = 6.31 × 10−4) and ZPR1 (p = 1.80 × 10−6, FDR = 0.016) were associated with SGA-induced TG changes; these genes were related to TG, HDL, and LDL levels and metabolic syndrome." (PMID 40830362, 2025). "Similar to APOA5, ZPR1 regulates TC, HDL and TG levels and has been associated with hypertriglyceridemia, metabolic syndrome and type 2 diabetes mellitus." (PMID 40830362, 2025). "Metabolic syndrome, T2DM, non-alcoholic fatty liver disease (NAFLD), and cardiovascular disease have all been associated with the ZPR1 variation rs964184 among different populations." (PMID 35782928, 2022). "Of these variants, rs17440396, rs10488699 and rs2187126 are associated with increased risk towards dyslipidemia and belong to BUD13 regulatory gene, while rs6589566 is risk reducing and belongs to ZPR1 regulatory gene." (PMID 28610615, 2017). "In the present study, we observed variants that belong to BUD13, ZPR1 genes and APOA5-APOA4 intergenic region as commonly associated with TC/LDLC and in turn with dyslipidemia." (PMID 28610615, 2017). "The present study aimed to identify associations linking allelic variants of the PCSK1, TMEM18, GPX5, ZPR1, ZBTB16, and PPARG1 genes with anthropometric and biochemical traits and metabolic diseases (obesity or metabolic syndrome) in an adult population from northwestern Mexico." (PMID 37761915, 2023). "On the other hand, the lack of association of the other SNPs (TMEM18 rs6548238 C allele, GPX5 rs445870 G allele, ZPR1 rs964184 G allele, and ZBTB16 rs7106340 T allele) with metabolic diseases (obesity or metabolic syndrome) in this work could have been influenced by the sample size." (PMID 37761915, 2023). "It is no surprise that ZPR1 levels are affected due to a high-fat diet since human studies with ZPR1 variant rs964184 show it to be involved with plasma triglycerides, metabolic syndrome, and T2DM, reinforcing the idea that this protein is involved in lipid metabolism." (PMID 34746842, 2021). "For instance, ZPR1 and BUD13 were well-documented for lipid level, HERPUD1 was found related to HDL-C in the Korean population, and the APOA5 and CETP also showed evidence of contributing to triglycerides, metabolic syndrome, and HDL-C." (PMID 35238325, 2022). "Also, rs180365 (LINC02702‐BUD13), rs964184 (ZPR1), rs662799 (ZPR1), rs10750097 (novel APOA5), rs6589574 (APOA1), rs562179 (novel SIK3), associated with lipid‐related traits and/or metabolic syndrome, showed evidence of interaction with TSS of APOA1." (PMID 40665476, 2025).
Obesity (10 papers, 2012 to 2026). Accumulation of substantial excess body fat. "Other expected single-variant associations include those in ZPR1, which codes for a regulatory protein known to bind several transcription factors that may influence obesity; variants within ZPR1 are known to affect triglyceride levels, as well as modulate HDL and total cholesterol levels." (PMID 33763119, 2021). "Researchers can look at brain tissues from patients diagnosed with Alzheimer's disease, insulin resistance, and obesity and measure the expression levels of ZPR1." (PMID 34746842, 2021). "Several relevant transcription factors (TFs) bind to the promoter region of ZPR1, including PPARG (functioning in insulin sensitivity and obesity) and HNF4A (triggering genes involved in glucose, fatty acid, and cholesterol metabolism)." (PMID 40665476, 2025). "In summary, the obtained results suggest that regions 8q22-24, 11q23-25, and 12q13-15 are very likely to contain genes like VPS13B, APOA5, ZPR1, BUD13, and FAIM2 that control obesity-related factors in Iranian families with MetS21,22,27,28,31,32." (PMID 33727680, 2021). "Additionally, the promoter site of ZPR1 binds peroxisome proliferator-activated receptor gamma (PPARG) proteins 1 and 2, which play a key role in insulin sensitivity and obesity." (PMID 31910446, 2020).
hypertriglyceridemia (9 papers, 2014 to 2025). A laboratory test result indicating elevated triglyceride concentration in the blood. "ZPR1 is a cell proliferation and signal transduction regulator protein with various physiological functions, and rs964184 of ZPR1 has been associated with T2DM hypertriglyceridemia in Asians." (PMID 33803960, 2021). "Thus, ZPR1 rs2075291 is associated with hypo-LDL cholesterolemia, hypertriglyceridemia, and hyperglycemia." (PMID 33803960, 2021). "Additionally, rs6589566 in the ZPR1 gene, which had been previously identified in KARE and HEXA cohort data, was also associated with hypertriglyceridemia in the genotype imputation." (PMID 31910446, 2020).
coronary artery disease (8 papers, 2010 to 2026). "BUD13 and ZPR1 were found to be associated across anatomical categories of coronary artery disease in an Indian study (Pranavchand, Kumar & Reddy, 2017)." (PMID 30631647, 2019). "After 3 years of dietary intervention, the altered postprandial triglyceride response induced by genetic variability in the rs964184 polymorphism of the ZPR1 gene can be modulated by a low-fat diet, better than by a Mediterranean diet, in patients with coronary artery disease." (PMID 35782928, 2022). "A Meta analysis of 14 GWAS studies on Europeans identified SNP rs964184 of ZPR1 gene to be significantly associated with HDL cholesterol, coronary artery disease and other lipid traits among Asian Indians and Chinese." (PMID 27257688, 2016). "Several SNPS, such as rs11591147 in PCSK9, rs1260326 in GCKR, rs10455872 in LPA, rs964184 in ZPR1, rs58542926 in TM6SF2, and rs182611493 in MAU2 have been clinically associated with multiple metabolic disorders, including coronary heart disease, hyperlipidemia, non-alcoholic fatty liver disease." (PMID 41608459, 2026). "The current study aimed to investigate whether long−term consumption of two healthy dietary patterns (LF diet or MedDiet) interacts with rs964184 SNP at the ZPR1 gene to modulate postprandial lipemia in coronary heart disease patients." (PMID 35782928, 2022). "The gene ZPR1 is known to interact with the triglyceride-associated gene APOA5, which plays an important role in regulating plasma triglyceride levels, a major risk factor for coronary artery disease (CAD)." (PMID 33763119, 2021).
type 2 diabetes mellitus (8 papers, 2012 to 2026). A type of diabetes mellitus that is characterized by insulin resistance or desensitization and increased blood glucose levels. "The chromosome 11 signal, rs964184, is located in 3’UTR of ZPR1/ZNF259 and has been associated with triglycerides, type 2 diabetes and abdominal aortic aneurysm (AAA)." (PMID 37666928, 2023). "The SNP of rs964184 in ZPR1 has recently been associated with type 2 diabetes mellitus (T2DM) in Japanese individuals." (PMID 27411854, 2016). "In addition, there have been studies showing that that ZPR1 contributed to the risk of type 2 diabetes mellitus." (PMID 30631647, 2019).
spinal muscular atrophy (4 papers, 2017 to 2025). A motor neuron disease that affect the muscles, and characterized by muscle weakness and atrophy resulting from progressive degeneration and irreversible loss of the anterior horn cells in the spinal cord (i.e., lower motor neurons) and the brain stem nuclei. "For example, reduced ZPR1 levels are associated with spinal muscular atrophy (SMA) and aberrant R-loop accumulation." (PMID 41305523, 2025). "ZPR1 is a modifier of R-loop-mediated neurodegeneration caused by alteration of senataxin function in spinal muscular atrophy and amyotrophic lateral sclerosis." (PMID 39070547, 2024). "ZPR1 has been identified as a key factor in R-loop resolution in the context of spinal muscular atrophy (SMA) and other neurological disorders." (PMID 41305523, 2025).
nonalcoholic fatty liver disease (3 papers, 2021 to 2026). "Through genome-wide association studies (GWAS), we identified 6 variants previously associated with nonalcoholic fatty liver disease (NAFLD) and validated 50 shared risk variants located in ZPR1 and FTO between the Taiwanese and European populations." (PMID 39923089, 2025).
atherosclerosis (2 papers, 2020 to 2026). A disease characterized by the build-up of fatty material and calcium deposition in the arterial wall resulting in partial or complete occlusion of the arterial lumen. "Since the SNPs at 11q23.3 region harbouring apolipoprotein coding genes namely APOA1, APOC3, APOA4, APOA5 and regulatory genes BUD13, ZPR1, SIK3 were found to be associated with defective lipid metabolism, this region was thought to play an important role in atherosclerosis and CAD risk." (PMID 33298998, 2020). "Five of them (ANGPTL4, APOB, BRAP, LPA, and ZPR1), were associated with increased levels of arteriosclerosis/atherosclerosis and risk of CVD, whereas four (DUSP13, FN1, IL6R, and MMP12) were associated with reduced levels of arteriosclerosis/atherosclerosis and risk of CVD." (PMID 42133815, 2026).
breast carcinoma (2 papers, 2019 to 2024). "Our results showed that ZPR1, the proteins shown to be upregulated in breast cancer tissue and correlated with cancer progression, was significantly downregulated after CB agonist exposure." (PMID 39527598, 2024). "Our proteomic analysis revealed proteomic profile alteration in MDA-MB-231 upon CB exposure that potentially led to breast cancer suppression, such as ZPR1/SHC1/MAPK-mediated cell proliferation and AXL/VAV2/RAC1-mediated cell motility pathways." (PMID 39527598, 2024).
Hypertension (2 papers, 2016 to 2020). The presence of chronic increased pressure in the systemic arterial system. "Eventually we identified a set of SNPs and environmental factors: rs5805 in the SLC12A3, rs12654264 in the HMGCR, rs2065412 and rs414936 in the ABCA1, rs96418 in the ZPR1 gene, waistline, degree of education, exercise frequency, hypertension, and the intake of meat." (PMID 32600448, 2020).
respiratory failure (2 papers, 2017 to 2022). The significant impairment of gas exchange within the lungs resulting in hypoxia, hypercarbia, or both, to the extent that organ tissue perfusion is severely compromised. "Poor innervation of diaphragm due to axonal degeneration of ZPR1-deficient phrenic motor neurons results in the loss of synapse and collapse of diaphragmatic rhythm, and respiratory failure." (PMID 35783101, 2022). "Further, the inactivation of Zpr1 in motor neurons results in phrenic nerve degeneration causing respiratory failure leading to perinatal lethality in mice." (PMID 35783101, 2022). "Spatiotemporal inactivation of Zpr1 gene in motor neurons down-regulates HoxA5 and causes defects in the function of phrenic motor neurons that results in respiratory failure and perinatal lethality in mice." (PMID 28811488, 2017). "To further investigate the cause of respiratory failure, we examined the effect of Zpr1 mutation on the development of phrenic nerves and innervation of the diaphragm." (PMID 28811488, 2017). "The results of this study demonstrate that the low levels of ZPR1 cause down-regulation of HoxA5 that leads to degeneration of phrenic motor neurons and respiratory failure in mice." (PMID 28811488, 2017). "In SMA, SMN-deficiency causes deregulation of ZPR1 and HoxA5 that lead to respiratory failure." (PMID 28811488, 2017). "Mutation of Zpr1 in motor neurons during early embryogenesis causes progressive loss of phrenic motor neurons and impairs the function of phrenic nerve that result in diaphragmatic paralysis, and respiratory failure, and stillbirth of mice." (PMID 28811488, 2017). "Respiratory distress caused by the low levels of HoxA5 in Zpr1 mutant mice and SMA mice is consistent with finding that HoxA5 deficiency causes degeneration of phrenic motor neurons and respiratory failure in mice." (PMID 28811488, 2017). "Together, these findings provide insight into the molecular basis of respiratory failure associated with SMA pathogenesis and identify ZPR1 and HoxA5 as potential targets that lay a foundation for developing therapeutic strategies to treat respiratory distress in SMA." (PMID 28811488, 2017).
alopecia (1 paper, 2026). Hair loss usually from the scalp. "These variants resembled previously reported pathogenic ZPR1 variants associated with a syndrome characterized by growth restriction, craniofacial abnormalities, alopecia, and hypoplastic kidneys." (PMID 42281740, 2026).
Alzheimer disease (1 paper, 2021). A progressive, neurodegenerative disease characterized by loss of function and death of nerve cells in several areas of the brain leading to loss of cognitive function such as memory and language. "Although ZPR1 is not the sole cause of Alzheimer's disease or vascular dementia, it may have a role in neuronal cell death and cognitive decline following a high-fat diet." (PMID 34746842, 2021).
carotid atherosclerosis (1 paper, 2021). A thickening and loss of elasticity of the walls of carotid arteries that occur with formation of atherosclerotic plaques. "In this study, the analysis of the ZPR1, APOA5, and GCKR genes in patients with SLE, showed that GCKR rs1260326 is strongly related to the presence of carotid atherosclerosis." (PMID 34065555, 2021).
cognitive decline (1 paper, 2021). "The two modalities of cognitive decline caused by low concentrations of ZPR1 are reduced brain-derived growth factor (BDNF) synthesis and neuron death, both occurring in the hippocampus." (PMID 34746842, 2021). "This article attempts to explain how ZPR1 contributes to the mechanism of high-fat diet-associated cognitive decline through three premises: i) high-fat diet results in cognitive decline, ii) ZPR1 deficiency also results in cognitive decline, and iii) high-fat diet results in ZPR1 deficiency." (PMID 34746842, 2021). "This brief article focuses on how the downregulation of ZPR1 by a high-fat diet can contribute to cognitive decline by directly influencing the concentration of PPAR-γ and indirectly reducing the concentration of BDNF to decrease neural plasticity." (PMID 34746842, 2021). "More experimental studies are needed to further understand how ZPR1 downregulation, a key molecular event, connects a high-fat diet to the eventual cognitive decline." (PMID 34746842, 2021). "Therefore, ZPR1 has the potential to be the connection between high-fat diet and cognitive decline." (PMID 34746842, 2021). "Several models demonstrated high-fat diet-mediated cognitive decline, but none explained how zinc finger protein 1 (ZPR1) plays a role." (PMID 34746842, 2021). "Therefore, more ZPR1 could mean more BDNF by increasing PPAR-γ transcription, possibly preventing cognitive decline." (PMID 34746842, 2021).
dementia (1 paper, 2021). Loss of intellectual abilities interfering with an individual's social and occupational functions. "This is a consequence of ZPR1 downregulation, occurring in later life, contributing to various forms of dementia triggered by a high-fat diet." (PMID 34746842, 2021).
developmental delay (1 paper, 2011). "There were no significant changes in the numbers and distribution of zpr1+ red and green cone cells or islet-1+ cells (data not shown), indicating selective effects on rods and not a general developmental delay." (PMID 21878117, 2011).
head and neck cancer (1 paper, 2025). A primary or metastatic malignant neoplasm affecting the head and neck. "We next examined SETX and ZPR1 expression in HPV-positive cervical and head and neck cancers using mRNA data from the TCGA database." (PMID 41305523, 2025). "In contrast, ZPR1 expression was significantly lower in HPV-positive cervical and head and neck cancers." (PMID 41305523, 2025). "Analysis of TCGA datasets revealed that ZPR1, but not SETX, mRNA expression is significantly reduced in HPV-positive cervical and head and neck cancers." (PMID 41305523, 2025).
myocardial infarction (1 paper, 2022). Gross necrosis of the myocardium, as a result of interruption of the blood supply to the area, as in coronary thrombosis. "rs964184 variant in the ZPR1 gene has been associated with blood lipids levels both in fasting and postprandial state and with the risk of myocardial infarction in high-risk cardiovascular patients." (PMID 35782928, 2022).
retinal degeneration (1 paper, 2020). Degeneration of the retina. "Since we did not detect expression of Zpr1 and SV2 in the eye, and because mutations in splicing factors have previously been shown to contribute to retinal degeneration, we hypothesized that the cells in the eye may be undergoing cell death." (PMID 33105605, 2020).
ZIKV infection (1 paper, 2020). "It is tempting to speculate that increases in ZPR1 protein during early stages of ZIKV infection reflects a protective host response, but this requires further studies." (PMID 32850779, 2020).
cardiovascular disease (4 papers, 2010 to 2022). "Lead SNPs nearby GCKR, FTO, ZPR1, and APOE were associated with various traits including cardiovascular diseases and/or PhenoAge biomarkers." (PMID 34038024, 2021).
neurodegenerative disease (3 papers, 2021 to 2024). A disorder of the central nervous system characterized by gradual and progressive loss of neural tissue and neurologic function. "It is possible that ZPR1 deregulation or disruption of ZPR1 protein-protein complexes may be a common contributing factor in the pathogenesis of neurodegenerative diseases caused by R-loop-mediated genomic instability but remains to be investigated." (PMID 35783101, 2022). "The emerging connections between R-loop levels and proteins with the potential to regulate R-loop resolution, such as SETX, ZPR1 and other components of RLRC, could be potential modifiers of neurodegenerative diseases." (PMID 39070547, 2024).
metabolic disease (2 papers, 2023 to 2024). A congenital disorder (due to inherited enzyme abnormality) or acquired (due to failure of a metabolically important organ) disorder resulting from an abnormal metabolic process. "Additionally, the rs964184 (ZPR1) has been reported to be associated with variations in lipid levels, as well as metabolic disorders such as NAFLD, T2DM, and CVD." (PMID 38997780, 2024).
infection (1 paper, 2024). The state of being infected such as from the introduction of a foreign agent such as serum, vaccine, antigenic substance or organism. "In addition to disrupting the activity of essential proteins involved in developing the neurosensory system, such as ZPR1, the infection plays an evasive role in mediated dysregulation." (PMID 37879254, 2024).
neurological disorders (1 paper, 2025). "ZPR1 is known to bind R-loops and SETX to recruit this helicase to these structures, although much of this work has been described in the context of neurological disease." (PMID 41305523, 2025).
ZPR1 also shares sentences with these, for which no sentence is quoted: hypercholesterolaemia (3 papers); hyperlipidaemia (3); cancer (2); Disorder of lipid metabolism (2); Insulin resistance (2); Stroke (2); abdominal aortic aneurysm (1); Abdominal obesity (1); amyotrophic lateral sclerosis 4 (1); arteriosclerosis (1); Cerebral atrophy (1); Cirrhosis (1); gout (1); heart failure (1); Hepatic steatosis (1); Hyperglycemia (1); medulloblastoma (1); tumor (1).